NLRP6 (NLR family pyrin domain containing 6)
Diseases named in the same sentence as NLRP6 in open-access papers (continued):
Sharing a sentence is not in itself a finding about the gene and the disease.
essential hypertension (5 papers, 2013 to 2024). Hypertension that presents without an identifiable cause. "To assess the possible association of NLRP6/AVR and ADM with essential hypertension in our Sardinian cohort, we examined single-point associations between NLRP6/AVR and ADM SNPs with hypertension susceptibility." (PMID 24147025, 2013). "Specific ADM and NLRP6/AVR variants affecting susceptibility to high blood pressure require further investigation." (PMID 24147025, 2013). "One of the NLRP6/AVR SNPs, rs7937440, demonstrated a significant association with hypertension in the total cohort after adjustment for multiple testing (P = 0.032)." (PMID 24147025, 2013). "Upon sex stratification, we detected one NLRP6/AVR SNP associated with decreased susceptibility to hypertension in males (rs7948797G, P = 0.029; OR = 0.73 [0.57–0.94])." (PMID 24147025, 2013). "Our data are consistent with the hypothesis that NLRP6/AVR contributes to hypertension susceptibility in humans." (PMID 24147025, 2013). "Our results revealed an association between NLRP6/AVR and ADM loci with male essential hypertension, suggesting the existence of sex-specific NLRP6/AVR and ADM variants affecting male susceptibility to essential hypertension." (PMID 24147025, 2013). "Subsequent analysis using SNPs spanning both the NLRP6/AVR and ADM transcription units confirmed their associations with essential hypertension in our Sardinian cohort." (PMID 24147025, 2013). "In conclusion, our results revealed an association between NLRP6/AVR and ADM loci and hypertension susceptibility in a northern Sardinian population, primarily affecting male essential hypertension." (PMID 24147025, 2013). "Here, we present evidence suggesting that the NLRP6/AVR and ADM loci contribute to hypertension susceptibility in a Sardinian population." (PMID 24147025, 2013). "In our GWAS, genes related to blood pressure (NLRP6, CREB5 and APOE) were found in regions associated with mtDNA abundance, providing a potential explanation between increased mtDNA abundance and reduced risk for hypertensive diseases." (PMID 33385171, 2021). "Single-point association analysis of SNPs in NLRP6/AVR and ADM with hypertension." (PMID 24147025, 2013). "Besides, NLRP6 inflammasome dysfunctions have been associated with adrenomedullin (ADM) loci and male essential hypertension, which suggests that NLRP6 inflammasome and potentially other NLRP inflammasome dysregulation promote pathogenesis of essential hypertension." (PMID 38644450, 2024). "The D11S1318 locus is a NLRP6/angiotensin vasopressin receptor, and it was suggested that NLRP6 might play a role in preventing the onset of ICH by reducing the genetic susceptibility of essential hypertension." (PMID 32596340, 2020). "Studies showed that biomarkers include PLD2, FLNA (filamin A), SMURF1, LINGO1, CACNA1H, NLRP6, NLRC3, CXCR2 and C5AR1 plays an important role in progression of hypertension." (PMID 36837510, 2023).
intracerebral hemorrhage (5 papers, 2020 to 2024). A cerebrovascular disorder characterized by bleeding into one or both cerebral hemispheres including the basal ganglia and the cerebral cortex. "Altogether, our study demonstrated that NPAS4, as a transcription factor, can exacerbate pyroptosis and transcriptionally activate NLRP6 in the acute phase of intracerebral hemorrhage in mice." (PMID 37176030, 2023). "By contrast, the NLRP6 inflammasome is a critical suppressor of cytokine production, which can protect against intracerebral hemorrhage and intestinal inflammation." (PMID 31127201, 2020). "Our previous study found that inhibiting NLRP6’s expression level could alleviate brain injury induced by ICH, suggesting that the activation of the NLRP6 inflammasome aggravates brain damage after intracerebral hemorrhage." (PMID 37176030, 2023). "In follow-up experiments, Nlrp6−/− mice should be raised to further explore the interaction of NPAS4 with the NLRP6 inflammasome in order to determine the potential mechanism of NPAS4 after intracerebral hemorrhage." (PMID 37176030, 2023). "The present study attempts to verify whether NLRP6 plays an important role in inflammatory reaction after intracerebral hemorrhage and identify the critical microRNA during the process." (PMID 32596340, 2020). "Additionally, it also confirmed that NPAS4 might aggravate pyroptosis and brain injury via activating the NLRP6 inflammasome after intracerebral hemorrhage in mice." (PMID 37176030, 2023). "Therefore, this study was designed to explore whether NPAS4 affects intracerebral hemorrhage and interacts with the Nlrp6 promoter." (PMID 37176030, 2023). "Also, the activation of NLRP6 inflammasome controls the growth of different types of cancer such as NHSCC, it is implicated in glucose regulation and it promotes the healing of brain injuries after intracerebral hemorrhages." (PMID 35650327, 2022).
Listeria infection (5 papers, 2018 to 2026). "Since our data indicated that live, replicating Listeria are required for NLRP6 activation, we next investigated if a disturbance of cellular homeostasis caused by Listeria infection drove NLRP6 activation." (PMID 41266655, 2026). "The reconstitution of IL-18 caused an outrageous outcome in Nlrp6−/− and Casp 11−/− mice by Listeria infection, suggesting that the involvement of IFN-I and caspase 11 in the production of IL-18 may worsen Listeria infection outcome." (PMID 34768828, 2021). "To identify which domains within NLRP6 sense Listeria infection, we created a set of chimeras between NLRP6 and NLRP3, using corresponding domains in NLRP3 as place holders to generate functional receptors." (PMID 41266655, 2026). "This also induced ASC speck formation, indicating that NLRP6 activation upon Listeria infection is conserved between mouse and human homologs (D and EV1D)." (PMID 41266655, 2026). "To understand how NLRP6 detects Listeria infection, we next characterized its mode of activation and the domain(s) implicated in this process." (PMID 41266655, 2026). "While S. aureus and S. Typhimurium did not cause elevated levels of ASC speck formation, L. monocytogenes infection resulted in up to 50% of ASC speck-positive cells (B and EV1C), indicating that Listeria infection triggered NLRP6 activation." (PMID 41266655, 2026). "The resulting NLRP3NACHT(NLRP6) chimera reacted to Listeria infection but was insensitive to nigericin and imiquimod treatment, thus mimicking the signal specificity profile of NLRP6." (PMID 41266655, 2026). "There is additional evidence that NLRP6 played a role in exacerbating the symptoms of systemic listeriosis by boosting the expression of IL-18." (PMID 36556283, 2022). "We next wanted to study NLRP6 activation by Listeria infection in a more physiological setting." (PMID 41266655, 2026). "In conclusion, our data suggest that during Listeria infection, NLRP6 ligand sensing mainly maps to its NACHT domain and that ATP binding and hydrolysis are an important prerequisite for NLRP6 inflammasome formation." (PMID 41266655, 2026). "To test the role of the FISNA in NLRP6 activation, we expressed two deletion mutants (aa108-129 and aa108-193) in GFP-ASCtg HEK293T and found that both deletions rendered the receptor unable to induce ASC speck formation upon Listeria infection." (PMID 41266655, 2026). "We thus conclude that, in contrast to Listeria infection, none of LTA, poly(I:C) or Taurine are ligands of NLRP6 that can activate this inflammasome in our model systems." (PMID 41266655, 2026).
acute kidney injury (4 papers, 2021 to 2025). Sudden and sustained deterioration of the kidney function characterized by decreased glomerular filtration rate, increased serum creatinine or oliguria. "Moreover, NLRP6 deficiency leads to upregulation of p-p38 MAPK, p-ERK, and p-IκBα in some diseases, such as allogeneic hematopoietic stem cell transplantation (allo-HSCT), peripheral nerve injury, and acute kidney injury (AKI)." (PMID 33918100, 2021). "However, during acute kidney injury (AKI), NLRP6 expression is markedly downregulated, leading to aberrant activation of MAPK signaling pathways." (PMID 40538805, 2025).
COVID-19 (4 papers, 2021 to 2024). A disease caused by infection with severe acute respiratory syndrome coronavirus 2. "The expression levels of NLRP3, NLRP6, IL-1β, and MARCH7 were decreased in COVID-19 patients, and this reflected the inhibition of the NLRP3 inflammasome pathway." (PMID 38004809, 2023). "Four of the five intestine-enriched proteins, i.e., ZG16, NLRP6, APOA4, and VIL1, showed decreased levels in serum of COVID-19 patients, whereas only CDHR2, a microvillar protein, showed elevated levels." (PMID 37739942, 2023). "Furthermore, the expression levels of NLRP3, NLRP6, IL-1β, and MARCH7 were decreased in COVID-19 patients, while they rose again in convalescent patients." (PMID 38004809, 2023).
enteritis (4 papers, 2019 to 2022). Inflammation of the small intestine. "Consistent with our results, WAS-induced small bowel inflammation (enteritis) is associated with inhibition of NLRP6, and a high fructose diet results in intestinal epithelial barrier damage and NLRP6 dysfunction." (PMID 35956340, 2022). "Sun et al17 reported that water‐avoidance stress (WAS) inhibited NLRP6 expression and WAS‐induced disruption of NLRP6 inflammasome signalling led to pathological changes of small intestine in the model of stress‐induced enteritis in mice." (PMID 30515917, 2019). "Under stress (water-avoidance stress) conditions, mice developed enteritis due to inhibition of epithelial NLRP6 expression by the elevated corticotropin-releasing hormone (CRH), while PPARγ agonist rosiglitazone induced NLRP6 expression, and reversed intestinal inflammation." (PMID 33717162, 2021). "It is possible that in bacterial infections, where myeloid cells are most important, NLRP6 seems to trigger destructive inflammation; however, during enteritis, involving non-hematopoietic cells such as intestinal epithelial cells, the NLRP6-mediated response is protective." (PMID 33910012, 2021).
gram-positive bacterial infections (4 papers, 2018 to 2023). Infections caused by bacteria that retain the crystal violet stain (positive) when treated by the gram-staining method. "Taken together, these novel findings show that NLRP6 serves as a negative regulator of neutrophil-mediated host defense during Gram-positive bacterial infection in the lungs through regulating both neutrophil influx and function." (PMID 30248149, 2018). "Interestingly, NLRP6 contribution is likely context-dependent, as it was shown to negatively regulate pulmonary host defense after gram-positive bacterial infection through neutrophil influx modulation." (PMID 38146368, 2023). "Interestingly, NLRP6 is also highly expressed in the respiratory tract but it plays a negative role in the lungs against gram-positive bacterial infection." (PMID 36224650, 2022).
metabolic syndrome (4 papers, 2021 to 2024). A cluster of metabolic risk factors for CARDIOVASCULAR DISEASES and TYPE 2 DIABETES MELLITUS. "Mice deficient in Nlrp6 are also more prone for intestinal inflammation and features of the metabolic syndrome mainly due to dysbiosis." (PMID 38315242, 2024). "This study highlighted the critical role of the gut microbiota in the pathogenesis of systemic autoinflammation and metabolic diseases by showing how the NLRP6 and NLRP3 inflammasomes negatively control the development of MASH and metabolic syndrome by altering them." (PMID 39070791, 2024).
non-alcoholic steatohepatitis (4 papers, 2013 to 2023). "Erysipelotrichia has been associated with nonalcoholic steatohepatitis, the pathophysiology of which involves the NLRP3 and NLRP6 inflammasomes." (PMID 33414380, 2021). "Both NLRP6 and NLRP3 inflammasomes negatively regulate the progression of non-alcoholic fatty liver disease (NAFLD) and non-alcoholic steatohepatitis (NASH) through the modulation of the gut microbiota." (PMID 37376638, 2023). "Although the role of NLRP6 inflammasome has not been well-studied in ALD, several reports have described its role during other types of chronic liver diseases such as non-alcoholic steatohepatitis (NASH)." (PMID 35053298, 2022).
ulcerative colitis (4 papers, 2017 to 2023). An inflammatory bowel disease involving the mucosal surface of the large intestine and rectum. "The NLRP6 has been associated with different inflammatory intestinal diseases such as ulcerative colitis or Crohn’s disease." (PMID 35650327, 2022). "Indeed, over-representation of Prevotellaceae has also been seen in the gut microbiota of mice bearing colonic epithelial cells deficient in the expression of the NLRP6 inflammasome, and in gut biopsies of ulcerative colitis patients." (PMID 28794801, 2017). "Further study indicated that the expression of NLRP6 was reduced in the epithelial layer of CD and ulcerative colitis (UC) patients." (PMID 30515917, 2019). "Furthermore, in patients with ulcerative colitis elevated levels of IL-18 inversely correlate with CYLD expression, suggesting that CYLD deubiquitination of NLRP6 could be a new therapeutic approach for treating intestinal inflammation." (PMID 35650327, 2022).
alcoholic hepatitis (3 papers, 2022 to 2023). Acute hepatitis resulting from ingestion of alcohol. "NLRP6 prevented the development of alcoholic hepatitis by blocking the NF-κB signaling pathway in hepatic stellate cells." (PMID 36613400, 2023). "Furthermore, NLRP6 is downregulated during NASH and alcoholic hepatitis, thus increasing the pro-inflammatory and profibrotic effects of NF-κB, promoting fibrosis, and increasing the severity of the diseases." (PMID 35650327, 2022).
bacterial pneumonia (3 papers, 2018 to 2025). Acute infection of the lung parenchyma caused by bacteria (e.g., Streptococcus pneumoniae, Haemophilus influenzae, Chlamydia pneumoniae, Mycoplasma pneumoniae, and Legionella pneumophila). "To this end, we have used NLRP6 KO mice to demonstrate how S. aureus exploits the NLRP6 inflammasome to dampen neutrophil function and enhance pyroptosis and necroptosis to increase mortality during acute bacterial pneumonia." (PMID 30248149, 2018).
chronic periodontitis (3 papers, 2020 to 2022). A chronic inflammatory process that affects the tissues that surround and support the teeth. "In order to observe the different distribution of NLRP family intuitively, immunohistochemistry was applied to analyze the expression characteristics of NLRP1, NLRP2, NLRP3, NLRP6, and NLRP12 in full-thickness gingival tissue samples obtained from severe periodontitis patients and healthy people." (PMID 32903638, 2020). "However, NLRP3, NLRP6, NLRP12, and AIM2 were expressed much higher in gingival tissues with periodontitis than in healthy group, especially for NLRP3 and NLRP12." (PMID 32903638, 2020).
colorectal tumors (3 papers, 2014 to 2022). "NLRP6 is a newly and specially characterized member of the NLRs family, which prevents the occurrence of diseases such as colorectal tumors and participates in the regulation of intestinal flora." (PMID 33918100, 2021). "Interestingly, gene expression profiling of colorectal tumors derived from WT and Nlrp6−/− mice revealed an increased expression of paracrine factors of the Wnt and NOTCH signaling cascades, underscoring a novel function of NLRP6 in controlling intestinal proliferation." (PMID 25071785, 2014).
fatty liver (3 papers, 2022 to 2023). "Deletion of NLRP6 alters the configuration of the intestinal microbiota, resulting in hepatic steatosis and inflammation via TLR4 signaling." (PMID 37664266, 2023). "In mice with fatty liver or steatohepatitis brought on by high-fat diets (HFD) or methionine-choline deficient diets (MCD), the expression of NLRP6 was downregulated." (PMID 37415625, 2023). "Using several mouse models for NASH, one study revealed that NLRP6 inflammasome activity performs beneficial functions in hepatocytes by reducing the extent of liver steatosis and inflammation." (PMID 35053298, 2022). "Similarly, abrogation of NLRP6 inflammasome activity did not significantly alter the extent of liver steatosis and serum triglyceride concentration." (PMID 35053298, 2022).
hepatic granuloma (3 papers, 2020 to 2022). A granuloma located in the liver. "The NLRP6 inflammasome promotes the onset of hepatic granuloma and collagen deposition, indicating that NLRP6 is a crucial trigger for SSLF." (PMID 35707547, 2022). "Furthermore, the lack of NLRP6 has been shown to significantly reduce periovular inflammation, collagen deposition in hepatic granulomas and mRNA levels of α-SMA and IL-13." (PMID 32431709, 2020).
Insulin resistance (3 papers, 2021 to 2025). Increased resistance towards insulin, that is, diminished effectiveness of insulin in reducing blood glucose levels. "In contrast, NLRP6 deficiency exacerbates inflammation in metabolic tissues, promoting the development of obesity, insulin resistance and fatty liver disease." (PMID 40433411, 2025). "It has been demonstrated that activation of NLRP6 promotes IL-18 secretion, which helps maintain intestinal barrier integrity and prevents excessive systemic inflammation that contributes to insulin resistance." (PMID 40433411, 2025). "In addition, the expression levels of NLRP6 and IL18 were highly associated between them and also with insulin resistance, strengthening their involvement in glucose metabolism." (PMID 38315242, 2024). "Taken together, these findings suggest that inflammasomes, including NLRP3, AIM2, NLRP1, NLRP6 and NLRC4 inflammasomes are involved in the regulation of insulin resistance, pancreatic β-cell health and diabetes." (PMID 40433411, 2025).
ischemic stroke (3 papers, 2023 to 2025). A stroke disorder caused by obstruction of blood flow to the brain, due to thrombotic (local blood clot formation) or embolic (due to a blood clot or other material traveling from another site) event. "In ischemic stroke, multiple inflammasomes (NLRC4, NLRP1, NLRP3, NLRP6, AIM2) have been implicated, with AIM2 uniquely recognizing cytosolic dsDNA to drive AIM2-ASC-caspase-1 complex formation and GSDMD-mediated pyroptosis." (PMID 41344159, 2025). "Our previously published research has confirmed that NLRP6 inflammasome activation contributes to inflammatory injury following ischemic stroke." (PMID 40831534, 2025). "Hitherto, the inflammasomes NLRC4, NLRP1, NLPR3, NLRP6 and AIM have been implicated in ischemic stroke." (PMID 37353794, 2023).
peripheral nerve injury (3 papers, 2015 to 2022). Injury to a peripheral nerve. "Together, our observations suggest that Nlrp6 contributes to recovery from peripheral nerve injury by dampening inflammatory responses independently of IL-1β and inflammasomes." (PMID 26253422, 2015). "Studies have unveiled that NLRP6 shows protective effects after a peripheral nerve injury, independent of inflammasomes." (PMID 36270983, 2022).
small cell lung carcinoma (3 papers, 2022 to 2025). Small cell lung cancer (SCLC) is a highly aggressive malignant neoplasm, accounting for 10-15% of lung cancer cases, characterized byrapid growth, and early metastasis. "Additionally, less studied inflammasomes like NLRP6 have been identified as critical for the M2 polarization of macrophages induced by small cell lung cancer (SCLC)-derived exosomes." (PMID 40141358, 2025). "In another experiment on small cell lung cancer (SCLC), NLRP6 was confirmed to be necessary for SCLC-derived exocrine to induce M2 polarization of macrophages and to promote SCLC metastasis." (PMID 37415625, 2023).